CD226 (CD226 molecule)
Diseases named in the same sentence as CD226 in open-access papers (continued):
Sharing a sentence is not in itself a finding about the gene and the disease.
cytomegalovirus infection (1 paper, 2021). A herpesvirus infection caused by Cytomegalovirus. "Another study showed that the expression of CD226 on inflammatory monocytes and splenic macrophages was increased after mouse cytomegalovirus infection." (PMID 34823548, 2021).
dacryoadenitis (1 paper, 2020). Inflammation and enlargement of the lacrimal gland. "Although female CD226 KO mice had similar levels of sialoadenitis as WT controls, male CD226 KO mice showed protection from dacryoadenitis." (PMID 33013915, 2020).
dilatation (1 paper, 2020). "As early as 1 week after MI, both WT and CD226 KO hearts developed decreased LV ejection fraction (LVEF) and increased LV chamber dimension, suggesting cardiac dysfunction and LV dilatation following MI." (PMID 32104514, 2020).
endometriosis (1 paper, 2024). The growth of functional endometrial tissue in anatomic sites outside the uterine body. "Little is known about the other inhibitory ICP pathways like T-cell immunoglobulin and the immunoreceptor tyrosine-based inhibitory motif domain (TIGIT)/DNAM (CD226)/CD155 or CD200/CD200R in the pathogenesis of endometriosis." (PMID 38892453, 2024). "However, the data are preliminary and insufficient to prove the role of TIGIT and CD226 in the pathogenesis of endometriosis." (PMID 38892453, 2024).
endothelial dysfunction (1 paper, 2016). In vascular diseases, endothelial dysfunction is a systemic pathological state of the endothelium (the inner lining of blood vessels) and can be broadly defined as an imbalance between vasodilating and vasoconstricting substances produced by (or acting on) the endothelium. "Our data demonstrate that CD226 knockdown protects against TNF-α-induced stress fiber formation and cytoskeleton remodeling, indicating that inflammation-induced CD226 increases may aggravate endothelial dysfunction in diabetic hyperglycemia." (PMID 26910838, 2016).
Glucose intolerance (1 paper, 2016). Glucose intolerance (GI) can be defined as dysglycemia that comprises both prediabetes and diabetes. "Although CD226 deficiency did not protect mice from HFD-induced weight gain, it reduced glucose intolerance, as shown by IPGTT and ITT." (PMID 26910838, 2016).
Hypertension (1 paper, 2021). The presence of chronic increased pressure in the systemic arterial system. "Xu et al27 found that CD226 might be involved in complications of vascular endothelial cells and platelets, suggesting that CD226 and PDGF may be involved in the vascular immune injury of pregnancy‐induced hypertension, which in turn triggers the related mechanism of intraluminal microthrombosis." (PMID 34132454, 2021).
inflammatory bowel disease (1 paper, 2024). A spectrum of small and large bowel inflammatory diseases of unknown etiology. "However, a recent study employing Treg-specific CD226 knockout mice revealed that the deletion of CD226 exacerbated the severity of GvHD and inflammatory bowel disease in animal models." (PMID 39349829, 2024).
Insulin resistance (1 paper, 2016). Increased resistance towards insulin, that is, diminished effectiveness of insulin in reducing blood glucose levels. "Notably, HFD reduced the increase in islet size in CD226 KO mice compared to WT C57CL/6 mice (p < 0.01), suggesting that CD226 deletion may slow the development of insulin resistance." (PMID 26910838, 2016).
interstitial lung disease (1 paper, 2021). A diverse group of lung diseases that affect the lung parenchyma. "An elevated TIGIT+CD226+ CD4 subset with enhanced effector function was observed in patients with DM, especially the patients complicated with interstitial lung disease." (PMID 33413573, 2021).
kidney failure (1 paper, 2024). An acute or chronic condition that is characterized by the inability of the kidneys to adequately filter the blood. "Moreover, the epithelial interactions were less active in the COVID + kidney failure group, especially inflammation-related signals, such as HGF, ICAM, WNT, CD226, and NECTIN, indicating a weakened immune response." (PMID 39202702, 2024).
lentivirus infection (1 paper, 2016). Virus diseases caused by the Lentivirus genus. "Furthermore, CD226 shRNA lentivirus infection increased membrane expression of the primary glucose transporter Glut1 whether or not TNF-α was present." (PMID 26910838, 2016).
Leukocyte-Adhesion Deficiency Syndrome (1 paper, 2022). Rare, autosomal recessive disorder caused by deficiency of the beta 2 integrin receptors (RECEPTORS, LEUKOCYTE-ADHESION) comprising the CD11/CD18 family of glycoproteins. "Interestingly, CD226-mediated NK cell activation is dependent on its association with LFA-1, as demonstrated by the impaired CD226-mediated cytotoxicity of NK cells from patients with leukocyte adhesion deficiency syndrome, who have a deficiency of the LFA-1 beta subunit." (PMID 36544762, 2022).
low grade glioma (1 paper, 2019). A grade I or grade II glioma arising from the central nervous system. "CD155 can form the same complex with CD96, CD226, AFDN, ITGAV, ITGB3, and AFDN in low-grade glioma (LGG) and GBM samples derived from the Biological Pathway Ex-change (BioPAX)." (PMID 31377744, 2019).
mental disorder (1 paper, 2017). A disease that has its basis in the disruption of mental process. "Moreover, the CD226 signaling pathway could potentially be considered as a novel candidate for intervention in mental disorders." (PMID 29299389, 2017).
Myositis (1 paper, 2021). "The frequency of TIGIT+CD226+ CD4 T cells was positively correlated with the Myositis Disease Activity Assessment (MYOACT) scores (n = 30, r = 0.4239, p = 0.0196)." (PMID 33413573, 2021).
nephritis (1 paper, 2021). Inflammation of renal tissue. "There were 16 patients with active nephritis at baseline, and they had a significantly elevated percentage of CD226+ B cells which had a significant correlation with renal SLEDAI-2K scores (ρ = 0.37; P = 0.009)." (PMID 34367178, 2021).
oral squamous cell carcinoma (1 paper, 2025). "In oral squamous cell carcinoma (OSCC), SPP1+ tumor-associated macrophages (TAMs) activate fibroblasts via SPP1-CD44 signaling and induce T cell exhaustion by promoting the ubiquitination and degradation of CD226 on T cells through CD155-CD226 signaling." (PMID 40904508, 2025).
renal fibrosis (1 paper, 2022). A final common manifestation of a wide variety of chronic kidney diseases characterized by glomerulosclerosis and tubulointerstitial fibrosis. "Moreover, the CD226+TIGIT– T cell population was associated with reduced Treg purity and suppressive capacity after expansion, and CD226 deficiency on Treg cells can aggravate renal fibrosis." (PMID 35587519, 2022).
steatosis (1 paper, 2016). Increased lipid within the cytoplasm of cells. "Histological analysis showed severe microvesicular steatosis in the liver and adipocyte hypertrophy in epididymal white adipose tissue (EWAT) in both WT C57BL/6 and CD226 KO HFD-fed mice." (PMID 26910838, 2016).
Thrombocytosis (1 paper, 2021). Increased numbers of platelets in the peripheral blood. "Further study indicated that the deletion of CD226 resulted in mild thrombocytosis and increased MK/platelet number." (PMID 34526904, 2021).
tuberculosis (1 paper, 2025). A chronic, recurrent infection caused by the bacterium Mycobacterium tuberculosis. "Similarly, tuberculosis patients show increased CD226+ NK and T cell subsets with enhanced production of CD107a and IFN-γ, suggesting CD226 as a biomarker for clinical outcomes and disease progression in tuberculosis." (PMID 40723878, 2025).
ZIKV infection (1 paper, 2018). "In our patient, more than 50% of the CD4+CD8dim T cells during acute ZIKV infection were CD45RA+CD226+CR-." (PMID 30596671, 2018).
tumor (476 papers, 2007 to 2026). "Elevated CD226 levels in tumor-infiltrating lymphocytes demonstrate a positive association with enhanced anti-tumor activity and favorable prognostic outcomes." (PMID 40723878, 2025). "The mutation of the Y319 site in CD226 increases the expression of CD226 and demonstrates potent anti-tumor immune capability." (PMID 39223632, 2024). "Transgenic mice expressing a Y319F mutation in CD226, which results in increased frequencies of CD226hiCD8 + TILs, demonstrate improved tumor control." (PMID 39349829, 2024). "CD226-deficient mice presented increased tumor development and mortality after transplantation of Meth A, 3-methylcholanthrene (MCA)-induced fibrosarcoma, 7,12-dimethylbenz[a]anthracene (DMBA)-induced papilloma tumor cells or CT2610,66." (PMID 39349829, 2024). "In metastatic melanoma, a high TIGIT/CD226 ratio in tumor Tregs is linked to increased CD25hiFoxp3+Treg cell frequencies and unfavorable clinical responses following ICI therapies." (PMID 39349829, 2024). "When the cytotoxicity of preactivated CD226-deficient OT-I T cells against MC38-OVA tumor cells was assessed, decreased tumor cell killing was observed due to the suboptimal formation of the IS." (PMID 39349829, 2024). "Eomes-dependent loss of CD226 related to tumor-infiltrating lymphocytes (TILs) with reduced anti-tumor functions." (PMID 38082437, 2023). "We also found that the percentages of CD8+CD226+T cells among CD8+T cells and CD8+CD226+T cells among CD8+T cells in the stromal cell region were significantly associated with tumor size (P=0.022, P=0.023, respectively)." (PMID 37056782, 2023). "The association between the percentages of CD226+ cells, CD226+ cells in the epithelial cell region, and CD226+ cells in the stromal cell region in tumor and clinical features of GC patients." (PMID 37056782, 2023). "This is consistent with the association between CD226 expression and potent immune infiltration in the tumor microenvironment." (PMID 36717657, 2023). "The correlation analysis showed that the expression of CD226 was positively correlated with the score of effector T cells but negatively correlated with that of immunosuppressive factors, such as Tregs and tumor-associated macrophages (TAMs)." (PMID 37056782, 2023). "We analyzed bulk RNA-seq from NSCLC tumor samples from three randomized clinical trials with atezolizumab and assessed how gene expression of CD226, PDCD1 (encoding PD-1), and TIGIT associated with clinical outcomes." (PMID 35263569, 2022). "Through complementary experiments involving human samples and mouse tumor models, two groups showed that loss of CD226 induces hypo-responsiveness in CD8+ T cells, and limits both TCR signaling and responsiveness to anti-PD-1 mAbs." (PMID 35874734, 2022). "Post-translationally, the CD226 ligand, CD155, within the tumor microenvironment has been implicated in the downregulation of CD226 on TILs." (PMID 35874734, 2022). "The research indicated that a high proportion of TIGIT+ Tregs and a high TIGIT/CD226 ratio in Tregs in the tumor immune microenvironment were associated with poor clinical prognosis." (PMID 35474948, 2022). "CD226 deficiency or blocking with anti-CD226 mAbs rendered tumor-bearing mice resistant to the combined treatment, which implies that CD226 is required for the efficacy of anti-PD-1 and anti-GITR mAb combination treatment." (PMID 33670993, 2021). "Consistent with the in vitro results, CD226 deficient mice also display a greater tumor burden than WT mice to a variety of tumors." (PMID 33670993, 2021). "Impaired NK-cell-mediated suppression of tumor growth by CD226 deficiency has been reported in B16/F10 or RM-1 lung-metastases mouse models." (PMID 33670993, 2021). "Additionally, an increased TIGIT to CD226 ratio in the tumour microenvironment has been associated with a higher frequency of activated Tregs, as well as an unfavourable prognosis." (PMID 38443832, 2024).
tumor (continued). "We also found that the percentages of CD8+CD226+T cells within CD8+T cells in the epithelial cell region and CD8+CD226+T cells within CD8+T cells in the stromal cell region were significantly associated with tumor stage (T stage) (P=0.013, P=0.047, respectively)." (PMID 37056782, 2023). "Meanwhile, lower levels of CD226+ NK cells have been linked to tumor immune escape." (PMID 37426809, 2023). "Furthermore, we found a positive correlation between CD226 and naïve B cells, memory B cells, and tumor-associated type I macrophages (M1)." (PMID 37056782, 2023). "As a result, CD226-deficient mice have impaired anti-tumor and antiviral T cell responses." (PMID 26347741, 2015). "Furthermore, considering that CD226 is expressed on various immune cell subsets, the genetic deletion of CD226 may alter their development or function, potentially contributing to the dysregulated tumor control observed in CD226-deficient mice." (PMID 39349829, 2024). "In addition, CD226 gene polymorphism was found to be directly related to tumor risk." (PMID 32850777, 2020). "These interactions collectively contribute to the hydrophobic interaction energies within the B7‐CD155 complex, modulating the CD155/T cell immunoreceptor with Ig and ITIM domains/CD226 axis to reshape the NK cell‐mediated tumor immune microenvironment." (PMID 40492418, 2025). "Similar to tumor cells, viruses can also exploit CD226-mediated pathways to evade immune surveillance." (PMID 40723878, 2025). "Using single-cell sequencing technology and flow cytometry, researchers systematically evaluated CD226 (DNAM-1) expression profiles in various tumor tissues and their paired normal tissues." (PMID 40463500, 2025). "In CD226-deficient mouse models, CD8+ T cells and NK cells exhibit defects in immune synapse formation, which impairs their anti-tumor immune functions." (PMID 40356928, 2025). "CD226 is an activating receptor mediating anti-tumor responses through recognition of its ligands that are upregulated in tumor cells." (PMID 41451217, 2025). "Specifically, TIGIT and PD-1 were upregulated, while CD226 was downregulated on NK cells, contributing to NK cell dysfunction and tumor immune evasion." (PMID 40231264, 2025). "CD155 on tumor cells induces CD226 degradation via phosphorylation and ubiquitination, impairing CD8+ T cell function and immunotherapy efficacy." (PMID 40723878, 2025). "With CD155 binding, TIGIT/CD96/CD226 transmits inhibition and activation signals to the immune system, and the integrated signals regulate immune functions and affect the anti-tumor immune response." (PMID 41181119, 2025). "In particular, TIGIT competes with CD226 for binding to ligands expressed on tumor cells and antigen-presenting cells (APCs)." (PMID 41303538, 2025). "CD155, an immune checkpoint molecule interacted with receptors of TIGIT/CD96/CD226 to exhibit co-inhibitory and co-stimulatory modulation on tumor immune microenvironment." (PMID 41181119, 2025). "It interacts with the activating receptor DNAX-associated molecule-1 (DNAM-1 [or CD226]), primarily expressed on T cells, NK cells, B cells, and monocytes, promoting early tumor recognition and elimination." (PMID 40478751, 2025). "CD8+ T cells are highly heterogeneous, and each subset plays a unique role in tumor immunity; therefore, we assessed the frequency of CD226+ expressing cells among different CD8+ T cell subsets with respect to the disease stage." (PMID 39777847, 2025). "A tumor vaccine expressing both CD226 and Ag85A induces stronger antitumor immunity in a colon carcinoma model, enhancing NK and CTL cytotoxicity and increasing IFN-γ-producing T cells." (PMID 40723878, 2025). "CD155-TIGIT/CD96/CD226 expression was evaluated by immunohistochemistry in tumor microenvironment (TME) by pathological professionals and the associations with clinical characteristics and prognosis were investigated under a cohort study design." (PMID 41181119, 2025).
tumor (continued). "Exosomes derived from IL-2/IL-15-treated NK cells carry CD226, enabling cytolytic activity at tumor sites and offering a novel immunotherapy strategy." (PMID 40723878, 2025). "It was found that IL-15 increased the expression of TIGIT and CD226 on TiNKs, augmented NK-cell-mediated melanoma cytotoxicity in vitro, and suppressed tumor metastasis in preclinical models together with TIGIT blockade." (PMID 38229100, 2024). "While the tumor environment seems to promote the accumulation of CD226loCD8 + T cells, CD226 downregulation is also found in resting T cells from healthy donors." (PMID 39349829, 2024). "Other NK receptors, such as NKp30, NKp44, and DNAM-1 (CD226), can also be expressed at varying levels on γδ T cells and contribute to tumor cell recognition and killing." (PMID 39144149, 2024). "Overall, detailed characterization of the intra-tumor expression of CD226, CD155, TIGIT, CD112, and CD112R can provide critical insights into the tumor immune landscape, supporting patient selection for more effective, tailored immunotherapeutic strategies." (PMID 39684559, 2024). "Recently, the importance of CD226 in tumor immunity has emerged, particularly in the context of anti-TIGIT therapy." (PMID 39349829, 2024). "The role of CD226 in modulating CD8 + T-cell-mediated antitumor responses has been assessed in various mouse tumor models." (PMID 39349829, 2024). "In SM1, CD226 was expressed in NK cells, and the corresponding ligand in tumor cells was only NECTIN2." (PMID 38528036, 2024). "CD2 and CD226, primarily on T and NK cells, are crucial for cell adhesion and recognition, known for their role in overcoming T cell exhaustion and boosting anti-tumor responses." (PMID 39349829, 2024). "It has been demonstrated that CD155, known as the poliovirus receptor (PVR), can interact with receptor CD226 on NK cells to impair NK cell function, thereby inducing tumor immune evasion." (PMID 38596684, 2024). "In the present study TIGIT and CD226 were expressed at higher levels by lymphocytes infiltrating CRC tumor tissues than adjacent, but the expression of CD155 was low or absent." (PMID 39113892, 2024). "DNAM1/CD226 is a potent activating receptor that has been shown to recognize two ligands overexpressed by tumor cells, namely PVR/CD155 which is considered as the main ligand and Nectin2/CD112." (PMID 39179536, 2024). "The discrepant effects of genetic deletion of CD226 and blockade of CD226 with an antibody on tumor control should be further assessed." (PMID 39349829, 2024). "We next looked at the expression of Cd226, Tigit, and Eomes, a transcription factor that has been shown to downregulate Cd226 expression in tumor-infiltrating T cells." (PMID 38533515, 2024). "DNAM-1 (CD226) plays a crucial role in the recognition and elimination of tumor cells by both NK and T cells." (PMID 39273034, 2024). "Similar functional defects in CD8+TILs with CD226 downregulation have also been observed in various mouse tumor models." (PMID 39349829, 2024). "Consistent with in vivo preclinical studies, in vitro evidence also suggests the importance of the CD226-PVR axis in CD8 + T-cell cytotoxicity against tumor cells." (PMID 39349829, 2024). "Aside from via pAgs, Vδ2Vγ9 T cells can also identify tumour cells through interaction with tumour‐associated surface proteins such as F1‐ATPase, NKG2D, TRAIL and CD226 which promote cytolytic activity." (PMID 38375329, 2024). "At the tumour site CD226 expression tends to be diminished due to PD-1 and TIGIT signaling, local regulation through TGF-ß, and proteasomal cleavage." (PMID 38440738, 2024). "Together, these findings suggest that TIGIT expression is upregulated on both CD96+CD8+ T cells and CD226+CD8+ T cells within the tumour microenvironment of LUAD." (PMID 38279870, 2024). "TIGIT/CD226 and CD96/CD226 gene expression ratios were substantially increased in tumor-infiltrating NK cells pre-treatment, indicating a disturbed balance shifted toward NK cell inhibition." (PMID 38181797, 2024).